E2F8 (E2F transcription factor 8)
Diseases named in the same sentence as E2F8 in open-access papers (continued):
Sharing a sentence is not in itself a finding about the gene and the disease.
breast carcinoma (continued). "The results showed that the expression levels of both E2F8 and MYBL2 were upregulated in female cancers compared to adjacent tissues, such as breast cancer (BRCA), ovarian cancer (OV), and cervical squamous cell carcinoma and endocervical adenocarcinoma (CESC)." (PMID 36814821, 2023). "A recent study reported that NONO in breast cancer regulates the expression of S-phase-associated kinase 2 (SKP2) and E2F transcription factor 8 (E2F8) at the post-transcriptional level, promoting breast cancer proliferation." (PMID 32106418, 2020). "We further demonstrate that E2F8 transcriptionally upregulates CCNE1 and CCNE2 via directly interacting with their respective gene promoter, which accelerates the transition of G1 to S phase of breast cancer cells." (PMID 26992224, 2016). "Moreover, TCGA data analysis revealed that E2F8 levels were significantly upregulated in breast cancer tissues compared to paired tumor-adjacent non-tumor tissues." (PMID 26992224, 2016). "Thus, aiming at exploring regulatory pathways for a high level of E2F8 in breast cancers, we discovered predictive inhibitors as follows: PIK-93 and NPK76-II-72-1, which could serve as a therapeutic strategy in patients with high expression of E2F8." (PMID 36814821, 2023). "For example, it has been found that NONO can regulate the proliferation of breast cancer cells by affecting the expression of SKP2 and E2F8." (PMID 40826746, 2025). "The RBP NONO plays an oncogenic role in breast cancer and modifies SKP2 and E2F8 in the post‐transcriptional phase." (PMID 34890108, 2022). "E2F8 levels remained low in non-tumor breast tissues but became markedly higher in patients with luminal A and further elevated in other subtypes including luminal B, Basal-like and Her2-enriched, suggesting that E2F8 might contribute to high proliferation rates in breast cancer." (PMID 26992224, 2016). "So, CUG2, E2F8, RAE1, and PTPA might not be the downstream targets of MBNL1-AS1 in breast cancer cells." (PMID 35518784, 2022).
lung cancer (23 papers, 2016 to 2024). A malignant neoplasm involving the lung. "E2F8 is a transcription factor for the HMGB3 gene whose overexpression is associated with poor prognosis in diverse types of cancer including non‐small cell lung cancer." (PMID 30913346, 2019). "E2F8 up-regulation is associated with poor prognosis in lung cancer and ovarian cancer." (PMID 31990034, 2020). "In addition, E2F8 overexpression was found to be significantly associated with poor overall survival in lung cancer." (PMID 29254182, 2017). "E2F1, E2F2, and E2F8 are E2F family members and are overexpressed in lung cancer cells (compared to normal human lung tracheobronchial epithelial cells)." (PMID 36209131, 2022). "E2f8 has been reported in liver cancer, lung cancer, cervical cancer, and other related diseases as it represses E2F transcriptional activation." (PMID 36559040, 2022). "This is consistent with previous in vitro work claiming an oncogenic function of E2F8 in lung cancer cell lines." (PMID 33922435, 2021). "For instance, E2F8 knockdown inhibited tumor formation in xenograft models of hepatocellular carcinoma and lung cancer in one study but significantly suppressed stress-induced skin cancer in another study using knockout mice." (PMID 34617871, 2021). "E2F8 is overexpressed in lung cancer and enhances cell proliferation, and depletion of E2F8 inhibited cell proliferation and tumor growth." (PMID 31990034, 2020). "Depletion of E2F8 inhibits cell proliferation and tumor growth in lung cancer, thus E2F8 can be considered as a novel therapeutic target for lung cancer." (PMID 31992202, 2020). "MTF treatment of lung cancer cells, in a similar manner as knockdown of E2F8, led to suppression of G1-S phase progression." (PMID 31261735, 2019). "E2f8 has been reported to show increased expression in lung cancer and to be important for the growth of lung cancer cells." (PMID 29720595, 2018). "Metformin down-regulated four E2F family members, E2F1, E2F2, E2F7, and E2F8 in lung cancer cells, with E2F8 being the most prominently down-regulated one." (PMID 29254182, 2017). "In this study, we analyzed global gene expression in metformin-treated lung cancer cells and found that E2F8 was significantly downregulated by metformin." (PMID 29254182, 2017). "A previous study has shown that Naphthol AS-TR phosphate (NASTRp), an inhibitor of cAMP response element-binding protein (CREB) transcriptional activity, significantly suppresses E2F8 expression in lung cancer." (PMID 29254182, 2017). "Upregulation of E2F8 promotes cell proliferation and tumorigenicity in breast, hepatocellular, and lung cancers." (PMID 29254182, 2017). "The mRNA levels of p21 were found to be inversely related to those of E2F8 in lung cancer cells while siRNA-mediated knockdown of p21 partly rescued siE2F8-induced arrest of the cell cycle." (PMID 29254182, 2017). "The effect of E2F8 overexpression on patient survival was analyzed using TCGA (The Cancer Genome Atlas) lung cancer data." (PMID 29254182, 2017). "Metformin inhibited mRNA expression of E2F8 in various lung cancer cell lines (H23, H226, A549, and H1299)." (PMID 29254182, 2017). "A target molecule responsible for cell cycle arrest by metformin was discovered using a gene chip array in lung cancer cells and the effect of metformin on E2F8 was assessed." (PMID 29254182, 2017). "Knockdown of E2F8 in lung cancer significantly increases the proportion of dead A549 cells in culture." (PMID 29254182, 2017). "Whereas E2F8 suppresses tumor development in the murine model of liver cancer, E2F8 contributes to the oncogenesis in other cancer types, including breast, cervical, and lung cancer." (PMID 38605607, 2024).
lung cancer (continued). "Additionally, E2F8 was shown to transcriptionally upregulate UHRF1 in lung cancer and cyclin D1 in hepatocellular carcinoma." (PMID 32823614, 2020). "We speculate that some of these pathways may be critical to the regulation of E2F8 expression in lung cancer." (PMID 29254182, 2017). "The present study suggests that metformin may induce cell cycle arrest at the G1 phase by suppressing E2F8 expression in lung cancer cells." (PMID 29254182, 2017). "One hundred six (13%) of 848 TCGA lung cancers overexpressed E2F8 mRNA." (PMID 29254182, 2017). "Moreover, E2F8 has also been found to be overexpressed in ovarian cancer, hepatocellular carcinoma and lung cancer." (PMID 26992224, 2016). "In addition, E2F8 promoted cancer cell proliferation, chemoresitance and invasion, and constituted a potential therapeutic target in hepatocellular carcinoma and lung cancer." (PMID 26992224, 2016). "Importantly, the overexpression of E2F8 has been shown to induce tumorigenesis and progression while its forced downregulation resulted in the inhibition of tumorigenic phenotypes in several human cancers, such as hepatocellular carcinoma, cervical cancer, lung cancer and colon cancer." (PMID 37094040, 2023). "Overexpression of miR-223-5p can significantly reduce expression of the messenger RNA (mRNA) and protein of E2F8 in NSCLC cells, thus inhibiting the proliferation, migration, and invasion of lung cancer cells." (PMID 33988228, 2021). "The following literature review confirmed that six of the nine TFs, including E2F8, MEIS, E4F1, BRCA1, GATA6, and IRX2, play essential roles in lung cancer progression." (PMID 29303984, 2018). "In addition, E2F8 may be associated with poor overall survival in lung cancer patients irrespective of histology." (PMID 29254182, 2017). "E2F8 was significantly upregulated in lung cancer compared to normal lung tissue and was essential for cancer cell maturation." (PMID 34617871, 2021). "The present study also observed worse overall survival in lung cancer patients with over-expression of E2F8 than in those with normal E2F8 expression, irrespective of histology." (PMID 29254182, 2017). "In addition, E2F8 was reported to transcriptionally upregulate cyclin D1 in hepatocellular carcinoma, and UHRF1 in lung cancer." (PMID 26992224, 2016).
hepatocellular carcinoma (17 papers, 2016 to 2025). A malignant tumor that arises from hepatocytes. "By binding with cell cycle regulatory element cyclin D1, E2F8 promotes hepatocellular carcinoma cell proliferation." (PMID 39999286, 2025). "E2F8 is involved in the regulation of cyclin D1 and promotes the accumulation of S-phase cells in hepatocellular carcinoma, further highlighting its role in cell proliferation." (PMID 39061176, 2024). "Studies have shown that E2F8 is upregulated in various cancers, including glioblastoma, ovarian cancer, and hepatocellular carcinoma, where it promotes cell proliferation and other effects." (PMID 39061176, 2024). "Previously we developed E2f7 and E2f8 transgenic (Tg) mice capable of blocking the proliferation of chemically-induced hepatocellular carcinomas, consistent with their role as tumor suppressors in the liver." (PMID 33922435, 2021). "Recent literatures demonstrated that E2F8 is strongly up-regulated in human hepatocellular carcinoma (HCC), showed to be tumor promoter to hepatocarcinogenesis." (PMID 31990034, 2020). "It has been shown that E2F8 contributes to human hepatocellular carcinoma via regulating cell proliferation and is considered as a potential therapeutic target of hepatocellular cancer." (PMID 30967126, 2019). "The overall association scores for hepatocellular carcinoma were 0.210 for HOXD9, 0.174 for NDST3, 0.111 for PZP, 0.106 for E2F8, 0.061 for ADRA2B, and 0.029 for COL15A1." (PMID 31754347, 2019). "Oncogenic mechanisms of E2F8 in hepatoma cell cycle need further experimental confirmation." (PMID 31990034, 2020). "As for hepatocellular carcinoma cell line (E118), E2F8, GABBPA and SOX11 were recovered." (PMID 30967126, 2019). "Furthermore HOXD-AS1 has been demonstrated to cooperate with miR-130a to regulate SOX4 and E2F8, and promote metastasis in hepatocellular carcinoma and glioma respectively." (PMID 30823895, 2019). "Therefore, it is possible that metformin regulates E2F8 through this pathway because metformin has been shown to suppress cAMP/CREB signaling through phosphorylation of CREB binding protein (CBP) in hepatoma cells." (PMID 29254182, 2017).
glioma (13 papers, 2018 to 2024). A benign or malignant brain and spinal cord tumor that arises from glial cells (astrocytes, oligodendrocytes, ependymal cells). "E2F8 and E2F2 have been also implicated in the maintenance of glioma stem cell phenotypes and cell transformation." (PMID 33804958, 2021). "E2F5, E2F7, and E2F8 were significantly upregulated in brain and CNS cancers relative to normal brain samples, while E2F1 and E2F3 were more highly expressed in normal brain samples in the ONCOMINE dataset." (PMID 34617871, 2021). "LncRNA HOXD-AS1 bound with miR-130a to downregulted the repression of E2F8, therefore regulating glioma development." (PMID 32943989, 2020). "HOXD-AS1 modulates the miR-130a/E2F8 (E2F transcription factor 8) axis in glioma, the miR-130a-3p/SOX4 (SRY-box 4) axis in liver cancer, and the miR-608/FZD4 (frizzled class receptor 4) axis in ovarian cancer." (PMID 29702599, 2018). "Besides, the positive correlation between Pontin and six E2F1 targets (AURKA, CDK1, CDK4, CCNA2, CCNB2, E2F8) assessed by GEPIA in glioma further supported the positive regulation of E2F1 targets expressions by Pontin." (PMID 33542204, 2021). "In addition, these interacted genes of E2F8 also related with many types of human malignancies including bladder cancer, non-small cell lung cancer, glioma, pancreatic cancer, melanoma, chronic myeloid leukemia, small cell lung cancer and prostate cancer." (PMID 31990034, 2020). "In addition, LncRNA HOXD-AS1 could compete with the transcription factor E2F8 to bind with miR-130a, and promoted cell migration and invasion in glioma cells." (PMID 30691465, 2019). "In particular, HEC1 promotes development of glioma through the regulation of cell proliferation, cell cycle, DNA repair, and TME formation, possibly through transcriptional activation of E2F8." (PMID 39021287, 2024). "HEC1 promotes development of glioma through the regulation of proliferation, cell cycle, DNA repair, and TME formation, possibly through transcriptional activation of E2F8." (PMID 39021287, 2024). "In glioma, HOXA-AS2 affects the expression of E2F8, E2F1, ATF3, and STAT1, promoting the proliferation of glioma stem cells (GSCs) and enhancing their aggressiveness." (PMID 38311789, 2024). "Analysis of high-grade glioma (HGG) indicated that E2F2 and E2F8 are highly correlated with oncogenes driving proliferation and therapeutic resistance and E2F8 independently predicts poorer survival." (PMID 33804958, 2021). "We observed that E2F2 and E2F8 mRNA levels are higher in GBM when compared to normal brain and gliomas grade II and III and, similarly to Msi1, their expression levels decrease during neuronal differentiation." (PMID 33804958, 2021).
ovarian carcinoma (12 papers, 2016 to 2025). A malignant neoplasm originating from the surface ovarian epithelium. "The upregulation of E2F8 was significantly associated with distant metastasis in the ovarian cancer patients (p = 0.041)." (PMID 32823614, 2020). "One study recently reported that atypical E2F8 knockdown inhibits the Wnt signalling pathway in ovarian cancer cells." (PMID 40026193, 2025). "Still, the biological role and clinical significance of E2F8 in epithelial ovarian cancer remained mostly unidentified." (PMID 32823614, 2020). "We determined that the expression of E2F8 at the mRNA and protein levels was significantly higher in the ovarian cancer cell lines OVCA433, TOV112D, and A2780 than in the normal control cells." (PMID 32823614, 2020). "The E2F8-knockdown ovarian cancer cell lines OVCA433, A2780, and TOV112D showed significant decreases in cell invasion, in comparison with the control cells." (PMID 32823614, 2020). "In ovarian cancer, E2F8 expression levels were significantly elevated in patients with residual disease >2 cm in diameter, and E2F8 down-regulation yielded longer OS." (PMID 31990034, 2020). "Overall, our results indicate that E2F8 enhances ovarian cancer cell proliferation, migration, and invasion, probably through the EMT and Notch signaling pathways." (PMID 32823614, 2020). "The IHC analysis determined that 63 ovarian cancer tissue samples showed more increased E2F8 expression than 5 normal ovarian tissue samples (p < 0.001)." (PMID 32823614, 2020). "In this study, we focused on E2F8 as a potential target for the inhibition of ovarian cancer progression." (PMID 32823614, 2020). "In vitro experiments using E2F8-knockdown ovarian cancer cell lines demonstrated that E2F8 knockdown inhibited cell proliferation, migration, and tumor invasion." (PMID 32823614, 2020). "To demonstrate the function of E2F8 in cell proliferation, migration, and invasion, we employed RNA interference to suppress E2F8 expression in ovarian cancer cell lines." (PMID 32823614, 2020). "In this study, we investigated the biofunctional role of E2F8 in epithelial ovarian cancer progression, and our results established a vital role for E2F8 as a promoter of ovarian cancer cell proliferation, migration, and invasiveness." (PMID 32823614, 2020). "The Kaplan–Meier survival analysis demonstrated that the ovarian cancer patients with high E2F8 levels had poorer progression-free survival compared to that of the patients with low E2F8 levels (p = 0.032)." (PMID 32823614, 2020). "Unfortunately, there is little research evidence between E2F8 and ovarian cancer diagnosis, staging, prognosis, and targeted drug therapy." (PMID 30967995, 2019). "Moreover, the TMA slide-based IHC analysis showed stronger nuclear E2F8 immunoreactivities in the ovarian cancer tissues than in the normal ovarian tissues." (PMID 32823614, 2020). "In addition, a wound-healing assay was used to assess the migration in siE2F8-transfected ovarian cancer cells; E2F8-knockdown cells exhibited reduced migration." (PMID 32823614, 2020). "Our findings provide substantial evidence that the upregulation of E2F8 plays an essential role in promoting ovarian cancer progression, and that E2F8 may represent a novel prognostic biomarker and therapeutic target for this disease." (PMID 32823614, 2020). "Thus, this is the first study to evaluate the potential of E2F8 as a therapeutic target for epithelial ovarian cancer treatment." (PMID 32823614, 2020). "We therefore investigated whether E2F8 is related to the invasion and migration of ovarian cancer cells." (PMID 32823614, 2020). "However, the biological role of E2F8 in the progression, particularly of ovarian cancer and its clinical implications, remains to be elucidated." (PMID 32823614, 2020). "Finally, the effect of E2F8 knockdown was investigated in a xenograft mouse model of ovarian cancer." (PMID 32823614, 2020).
ovarian carcinoma (continued). "Hence, we explored the bio-functional effects of E2F8 knockdown on ovarian cancer cell lines in vitro and in vivo." (PMID 32823614, 2020). "Moreover, the prognosis of the ovarian cancer patients with high E2F8 expression was poorer than that of the patients with low E2F8 expression." (PMID 32823614, 2020). "Importantly, we demonstrated that the overexpression of E2F8 has clinically relevant prognostic significance in ovarian cancer patients." (PMID 32823614, 2020). "Then, we examined the effects of E2F8 on the ovarian cancer cells." (PMID 32823614, 2020). "Herein, we demonstrated that E2F8 upregulates the EMT and Notch signaling pathways, and a further follow-up study is being planned to support the hypothesis that E2F8 promotes ovarian cancer progression by upregulating multiple cell cycle regulators." (PMID 32823614, 2020). "Furthermore, our results reveal a potential molecular mechanism by which E2F8 promotes cell proliferation and invasiveness in ovarian cancer upon activating the EMT and Notch signaling pathways." (PMID 32823614, 2020). "In the E2F family of transcription factors, E2F2, E2F3, E2F4, and E2F8 expression is increased and may play oncogenic roles in ovarian carcinoma, and exert the same effects as E2F1." (PMID 28146423, 2017). "Hence, we aimed to investigate the involvement of E2F8 in the progression of ovarian cancer." (PMID 32823614, 2020). "E2F is a transcription factor that controls the expression of all cell division genes, of which E2F8 is significantly increased in HCC and ovarian cancer." (PMID 34512165, 2021). "The E2F8 mRNA expression was significantly higher (p = 0.0078) in ovarian cancer tissues (n = 115) than in noncancerous tissues (n = 60)." (PMID 32823614, 2020).